UTF1 (undifferentiated embryonic cell transcription factor 1)
Description:
Acts as a transcriptional coactivator of ATF2.
Tractability: No criterion of Open Targets' tractability assessment is met for any kind of drug.
Gene: Protein-coding gene on chromosome 10 (133,230,217 to 133,231,558, forward strand). Ensembl gene ENSG00000171794.
Subcellular location: Nucleus
Gene Ontology:
Molecular function: protein binding; transcription coactivator activity
Biological process: male gonad development; positive regulation of transcription by RNA polymerase II; regulation of transcription by RNA polymerase II
Cellular component: nucleus
Genetic constraint (gnomAD): Loss-of-function variants: 12 observed, 5.35 expected, observed/expected ratio (o/e) 2.24. That is too few expected variants to judge how well the gene tolerates losing a copy. Missense variants: 542 observed, 308.11 expected, observed/expected ratio (o/e) 1.76, 90% interval 1.64 to 1.89. Synonymous variants: 341 observed, 179.78 expected, observed/expected ratio (o/e) 1.9, 90% interval 1.73 to 1.98.
Homologues: Orthologues: chimpanzee UTF1 (99% identical), dog UTF1 (77% identical), Drosophila melanogaster meso18E (16% identical), zebrafish si:dkey-261j15.2 (9% identical). Paralogues in human: MSANTD2 (21% identical), MSANTD7 (19% identical).
Diseases named in the same sentence as UTF1 in open-access papers:
UTF1 is named in the same sentence as 22 diseases in open-access papers, as found by Europe PMC text mining. Sharing a sentence is not in itself a finding about the gene and the disease. The quoted sentences say what the papers report.
cervical cancer (6 papers, 2012 to 2023). A primary or metastatic malignant neoplasm involving the cervix. "Surprisingly, direct bisulfite pyrosequencing revealed that the inhibition of DNA methyltransferase by 5-aza-2′-deoxycytidine was associated with decreased UTF1 gene methylation and expression in two cervical cancer cell lines of the four tested." (PMID 22880087, 2012). "Previous studies have reported that UTF-1 is expressed in various human epithelial-type neoplasias, such as cervical cancer." (PMID 25435811, 2014). "A genome-wide promoter methylation screening revealed a strong hypermethylation of Undifferentiated cell Transcription Factor 1 (UTF1) promoter in cervical cancer in comparison with normal ectocervix." (PMID 22880087, 2012). "miR-148a also repressed proliferation of bladder cancer cells by establishing a positive feedback loop between ERBB3/AKT2/c-myc signaling and DNMT1 or by regulating expression levels of DNMT1 and undifferentiated embryonic cell transcription factor 1 (UTF1) in cervical cancer cells." (PMID 36959680, 2023). "And the low expression of UTF1 may connect with poorer prognosis among patients with cervical cancer." (PMID 25435811, 2014). "The expression of UTF1 was subsequently detected in germ cell neoplasms, and cervical cancer." (PMID 25435811, 2014). "Our results suggest that UTF1 promoter methylation profile could be used as a biomarker for cervical cancer diagnosis and raise the questions about the mechanisms involved in the regulation of its expression in epithelial tumors." (PMID 22880087, 2012). "With this technique, we showed that UTF1 hypermethylation status might be a useful biomarker to discriminate normal Ecto and LSIL from HSIL and SCC and to improve cervical cancer diagnosis." (PMID 22880087, 2012).
embryonal carcinoma (3 papers, 2011 to 2021). A non-seminomatous malignant germ cell tumor characterized by the presence of large germ cells with abundant cytoplasm resembling epithelial cells, geographic necrosis, high mitotic activity, and pseudoglandular and pseudopapillary structures formation. "Utf1 has been described to control pluripotency and differentiation of embryonic stem (ES) and embryonal carcinoma (EC) cells." (PMID 33753728, 2021). "Both fgf4 and utf1 are typical Sox2 target genes, therefore, we used two biotin-labeled DNA probes, covering the Sox2-binding sites in fgf4 and utf1 respectively, to enrich endogenous Sox2 from P19 embryonal carcinoma cells." (PMID 22046437, 2011). "For example, Utf1, a transcription factor required for the proper differentiation of embryonic carcinoma cells and ESCs40, is enriched after chromosome sorting, while Nanog, Oct4 (Pou5f1) and Klf4, although detected, show no significant enrichment in sorted chromosome samples." (PMID 32807789, 2020).
Azoospermia (2 papers, 2020 to 2024). Absence of any measurable level of sperm,whereby spermatozoa cannot be observed even after centrifugation of the semen pellet. "On the other hand, UTF1 is a specific marker for the undifferentiated compartment and was utilized in the human non-obstructive azoospermia testis in this study." (PMID 38486279, 2024). "Our results from immunohistochemistry of non-obstructive azoospermia revealed a low expression of sox9 and UTF1 in the locations that were not related to the Sertoli cells and undifferentiated spermatogonia respectively." (PMID 38486279, 2024). "Confocal scanning UV-laser microscope images proved the expression of UTF1 and sox9 out of the common compartment of seminiferous tubules of non-obstructive azoospermia." (PMID 38486279, 2024).
developmental delay (2 papers, 2013 to 2017). "UTF1 homozygous mutations provoke a developmental delay that becomes apparent at the mid-gestational stage." (PMID 23874519, 2013). "Because of this developmental delay, newborn UTF1 homozygous mutant mice with a C57BL/6J background did not survive for more than 2 days." (PMID 23874519, 2013).
germ cell neoplasms (2 papers, 2015 to 2016). "In the testis, it has been evidenced that UTF1 is expressed in a subset of spermatogonial cells and germ cell neoplasms, making the SSCs maintain the ability of differentiation." (PMID 26221533, 2015). "We found a correlation between PIM1/2 expression and VENTX, SOX15, UTF1, NANOG, POU5F1P4, POU5F1P3, and POU5F1B expression in male germ cell tumors." (PMID 27901106, 2016).
germ cell tumors (2 papers, 2012 to 2016). A benign or malignant, gonadal or extragonadal neoplasm that originates from germ cells. "UFT-1 and Rex1 are expressed in Testicular germ cell tumors (TGCT), and the high abundance of UTF-1 in spermatocytic seminomas is consistent with the hypothesis that this tumour type originates from spermatogonia." (PMID 22634835, 2012).
infertile (2 papers, 2015 to 2021). "Collectively, The Pten-deletion-induced reduction of PLZF and increased expression of UTF1 apparently disturb the balance of self-renewal and differentiation of SSCs, leading to the depletion of spermatogonial cells and infertility with age." (PMID 26221533, 2015).
nocardiosis (2 papers, 2017 to 2022). Nocardiosis is a local (skin, lung, brain) or disseminated (whole body) acute, subacute, or chronic bacterial infection. "The most recent common ancestor of the Vietnamese strains differed by 220 SNPs from the next closest known strain, UTF1, which was isolated from cultured yellowtail that succumbed to nocardiosis in 2008 in Miyazaki Prefecture, Japan." (PMID 35786440, 2022). "In this study, using Single Molecule, Real-Time (SMRT) DNA sequencing, the complete genome nucleotide sequence of N. seriolae UTF1 isolated from a yellowtail that succumbed to nocardiosis in Japan was determined and annotated." (PMID 28257489, 2017).
breast carcinoma (1 paper, 2014). "The result showed that the low expression level of UTF-1 mRNAs in breast cancer patients was significantly associated with metastasis lymph nodes and tumor size." (PMID 25435811, 2014). "Real-time polymerase chain reaction (real-time PCR) was applied to detect the expression of UTF1 mRNA in the 55 pairs of samples of breast cancer tissues and match normal tissues." (PMID 25435811, 2014). "The findings of this study present a novel knowledge of UTF1 and a potential future prospect for breast cancer treatment." (PMID 25435811, 2014). "The present study was undertaken to examine the expression of UTF1 in breast cancer tissues by using a validated specific and sensitive real-time quantitative PCR assay." (PMID 25435811, 2014). "The UTF-1 mRNA levels in normal tissues were significantly higher than those observed in breast cancer tissues (p < 0.001)." (PMID 25435811, 2014). "In the current study, real-time quantitative PCR was used to compare the expressions of UTF-1 mRNAs in 55 breast cancers and their matched normal tissues, which allows detecting UTF-1expression in breast tissues with very low level." (PMID 25435811, 2014). "We showed that UTF-1 was lower expressed in breast cancer tissues than corresponding normal tissues." (PMID 25435811, 2014). "In the present study, we found the relative quantity of UTF-1 mRNA mRNA in 55 samples of breast cancer tissues as determined by real-time PCR." (PMID 25435811, 2014). "Of the 55 samples of breast cancer tissues and matched normal tissues adjacent to the tumor, expression of UTF-1 was detected in total samples." (PMID 25435811, 2014). "Among the 55 pairs of samples of breast cancer tissues and match normal tissues adjacent to the tumor, the UTF1 mRNA levels in normal tissues were significantly higher than those observed in breast cancer tissues (p < 0.001)." (PMID 25435811, 2014). "In the present study, we evaluate the expression of UTF1 in breast cancer and its correlation with clinicopathological parameters." (PMID 25435811, 2014). "UTF-1 mRNA was expressed more predominantly in normal tissues adjacent to the tumor than it was expressed in breast cancer tissues." (PMID 25435811, 2014). "Decreased expression of UTF1 mRNA in breast cancer tissues was maybe one of the factors impact on tumorigenes in breast cancer patients." (PMID 25435811, 2014). "Our present study clarify that UTF-1 protein could act as a potential biomarker for prognosis assessment of breast cancer." (PMID 25435811, 2014). "In breast cancer tissues, the UTF-1 mRNA levels ranged from 0.008 to 6.263 with a median of 1.517." (PMID 25435811, 2014). "Here, we examined fifty-five cases of breast cancer tissues for the potential difference of UTF1 expression in breast cancer tissues and their matched normal tissues, and to assess the relationship between UTF1 expression and clinicopathological parameters in breast cancer patients." (PMID 25435811, 2014). "Expression of UTF1 in breast cancer tissues were confirmed in this study." (PMID 25435811, 2014). "We hypothesize that UTF1 may play a role in the oncogenesis of breast cancer." (PMID 25435811, 2014). "Based on our findings, UTF1 gene could be a potential target for the treatment of breast cancer." (PMID 25435811, 2014). "According to median expression level of UTF-1, 55 cases of breast cancer patients were divided into two groups, high UTF-1 expression group (UTF-1 expression level >1.517) and low UTF-1 expression group (UTF-1 expression level ≦ 1.517)." (PMID 25435811, 2014). "Although UTF1 has been extensive studied in other cancers, no investigation has been conducted in breast cancer." (PMID 25435811, 2014).
cryptorchidism (1 paper, 2013). The failure of one or both testes of a male fetus to descend from the abdomen into the scrotum during the late part of pregnancy. "Recently, similar to our data, in rats, where cryptorchidism was induced by flutamide injections into pregnant females, a decrease of undifferentiated embryonic cell transcription factor 1 (UTF1) positive early spermatogonia cells was detected." (PMID 24098584, 2013).
Cryptozoospermia (1 paper, 2023). A type of oligozoospermia in which spermatozoa can be detected in an ejaculate only after centrifugation and inspection of the pellet. "More importantly, an enhanced and prolonged expression of EGR4 was noticed in SPGs (also resembled the SSC-1 cells in Sohni's study 67), which could act as a transcriptional factor and inhibit the expression of UTF1 in part of SPGs from cryptozoospermia patients." (PMID 37151874, 2023).
endometriosis (1 paper, 2012). The growth of functional endometrial tissue in anatomic sites outside the uterine body. "This is supported by the fact that, in endometriosis, an estrogen-dependent disease characterized by the presence of endometrium outside the uterine cavity, higher levels of UTF1 mRNA were found in comparison with normal endometrium." (PMID 22880087, 2012).
lymph node metastasis (1 paper, 2014). "UTF1 mRNA levels expression correlated with lymph node metastasis (p = 0.002) and tumor size (p < 0.001)." (PMID 25435811, 2014).
skin cancer (1 paper, 2012). "One possible explanation could be related to a role of UTF1 in cell division as it was proposed for the B lymphoma Mo-MLV insertion region 1 homolog (BMI-1) gene in skin cancer but the mechanism behind these observations is still unknown." (PMID 22880087, 2012).
cancer (4 papers, 2011 to 2020). A tumor composed of atypical neoplastic, often pleomorphic cells that invade other tissues. "Previous studies have shown the expression of UTF-1 cells was identified in a subpopulation of stem cell-like cells and the expression of UTF-1 may influence the susceptibility of cancer cells to chemotherapeutic agents and radiotherapy." (PMID 25435811, 2014). "Previous reports have indicated that there was a possible correlation of undifferentiated embryonic cell transcription factor-1 (UTF1) with the biological of cancer cell." (PMID 25435811, 2014). "Here, we demonstrated the presence of UTF1 in normal and tumor squamous epithelial tissues, as well as in cancer cell lines." (PMID 22880087, 2012). "In cancer cell lines, except for CasKi cells, UTF1 mRNA was more expressed, than in NCCIT differentiated with RA (p<0.001 vs NCCIT+RA)." (PMID 22880087, 2012). "By direct bisulfite pyrosequencing of DNA isolated from liquid-based cytological samples, we showed that UTF1 promoter methylation increases with lesion severity, the highest level of methylation being found in carcinoma." (PMID 22880087, 2012). "The expression of UTF1 mRNA was compared to that of the NCCIT carcinoma cell line which express high level of UTF1 while it was very low when these cells are treated with retinoic acid (RA)." (PMID 22880087, 2012). "This prompted us to evaluate UTF1 status in human beast cancer." (PMID 25435811, 2014). "In a cancer context, UTF1 was shown to be highly expressed in germ cells tumors." (PMID 22880087, 2012). "Thus, UTF1 plays an important role in stem cells, and the expression of UTF1 cancer cells may have stem cell-like features." (PMID 25435811, 2014). "Therefore, we can postulate that UTF1 upregulation by itself might participate to the global gene expression alterations leading to cancer development by locking tumor-specific gene expression pattern through its fixation to chromatin." (PMID 22880087, 2012). "In vitro experiments allowed to detect UTF1 in the nucleus of epithelial somatic cancer cell lines even in the absence of its main known regulators, Sox2 and Oct4A." (PMID 22880087, 2012). "Two of the genes (KIF17 and ATP8A2) showed no methylation in either cancer or matched tissues, and eight genes (EPHA4, OVOL1, UTF1, ADAM8, BOLL, FOXE3, GUCY1A2, and ADCY5) were equally methylated in the two groups." (PMID 21625442, 2011). "Immature testicular tissue from untreated cancer patients without any evidence of compromised testicular function (NT group) was used to characterize developmental-related changes in spermatogonial marker expression profiles of MAGEA4, UTF1, PCNA, and 5mC." (PMID 31947706, 2020).
tumor (4 papers, 2011 to 2016). "Moreover, tumor size was different between high expression UTF-1 versus low expression UTF-1 (1.34 vs. 2.46), the difference also have statistically significant (p < 0.001)." (PMID 25435811, 2014). "We also showed that, in vitro, UTF1 expression is not restricted to SC and that it is localized in the nucleus of somatic tumor cells independently of Oct4A and Sox2 expression." (PMID 22880087, 2012). "In SCC, staining of UTF1 was significantly stronger than in Ecto and LSIL in 75% of the samples (14 cases) (p<0.01 vs Ecto and LSIL) and was expressed by all the cells within tumor samples." (PMID 22880087, 2012). "The UTF1 expression pattern that we observed did not fit the definition of CSC which account for a very small proportion of cells within tumor mass." (PMID 22880087, 2012).
UTF1 also shares sentences with these, for which no sentence is quoted: bladder cancer (1 paper); Cirrhosis (1); gastric cancer (1); osteosarcoma (1); seminoma (1); teratoma (1).